MIEF2 (mitochondrial elongation factor 2)
Description:
Mitochondrial outer membrane protein involved in the regulation of mitochondrial organization. It is required for mitochondrial fission and promotes the recruitment and association of the fission mediator dynamin-related protein 1 (DNM1L) to the mitochondrial surface independently of the mitochondrial fission FIS1 and MFF proteins. Regulates DNM1L GTPase activity.
Synonyms: MID49; SMCR7; MGC23130; D3B; COXPD49
Tractability: Small molecule: a structure with a bound ligand is known. Antibody: UniProt predicts a signal peptide or a membrane-spanning region. PROTAC: ubiquitination databases record sites on it.
Gene: Protein-coding gene on chromosome 17 (18,259,527 to 18,266,552, forward strand). Ensembl gene ENSG00000177427.
Subcellular location: Mitochondrion outer membrane
Gene Ontology:
Molecular function: protein binding
Biological process: mitochondrial fusion; mitochondrion organization; positive regulation of mitochondrial fission; positive regulation of protein targeting to membrane; regulation of mitochondrion organization
Cellular component: mitochondrial outer membrane; mitochondrion; peroxisome
Genetic constraint (gnomAD): Loss-of-function variants: 2 observed, 8.79 expected, observed/expected ratio (o/e) 0.23, 90% interval 0.092 to 0.72. That is too few expected variants to judge how well the gene tolerates losing a copy. Missense variants: 569 observed, 563.14 expected, observed/expected ratio (o/e) 1.01, 90% interval 0.94 to 1.08. Synonymous variants: 275 observed, 261.45 expected, observed/expected ratio (o/e) 1.05, 90% interval 0.95 to 1.16.
Gene-disease validity (ClinGen):
ClinGen rates the evidence that MIEF2 causes each of these diseases.
mitochondrial disease (autosomal recessive): Limited.
Homologues: Orthologues: chimpanzee MIEF2 (99% identical), macaque MIEF2 (98% identical), guinea pig MIEF2 (83% identical), pig MIEF2 (82% identical), mouse Mief2 (80% identical), rat Mief2 (79% identical), rabbit MIEF2 (75% identical), tropical clawed frog mief2 (47% identical), zebrafish mief2 (22% identical). Paralogues in human: MIEF1 (46% identical).
Diseases named in the same sentence as MIEF2 in open-access papers:
MIEF2 is named in the same sentence as 25 diseases in open-access papers, as found by Europe PMC text mining. Sharing a sentence is not in itself a finding about the gene and the disease. The quoted sentences say what the papers report.
ovarian carcinoma (10 papers, 2020 to 2025). A malignant neoplasm originating from the surface ovarian epithelium. "Researchers have shown that MIEF2 expression is notably increased in ovarian cancer and promotes cell growth and metastasis." (PMID 38779765, 2024). "In ovarian cancer, miR-424–5p inhibits mitochondrial elongation factor 2 (MIEF2), which regulates mitochondrial fission, inhibits glucose metabolism from oxidative phosphorylation to glycolysis, and inhibits tumor growth." (PMID 35004688, 2021). "Bioinformatics analysis indicated that high expression of MIEF2 predicted a poor prognosis in ovarian cancer patients." (PMID 33414447, 2021). "Recently, it has been demonstrated that mitochondrial elongation factor 2 (MIEF2) over-expression drives the progression of ovarian cancer by enhancing lipid accumulation." (PMID 34771647, 2021). "Our results suggest that MIEF2 overexpression-mediated mitochondrial dysfunction plays a critical role in the reprogramming of lipid metabolism in ovarian cancer cells." (PMID 33414447, 2021). "Recently, we have demonstrated that MIEF2 is frequently up-regulated and contributes to both growth and metastasis of ovarian cancer (OC) cells." (PMID 33414447, 2021). "In this study, we conduct the first study on MIEF2 in ovarian cancer to clarify its expression pattern, clinical significance, biological effects in this malignancy." (PMID 33317572, 2020). "The expression of MIEF2 was firstly evaluated in tumor and corresponding peritumor tissues from 30 patients with ovarian cancer (OC) using quantitative real-time PCR (qRT-PCR) analysis." (PMID 33317572, 2020). "However, the expression, clinical significance and biological functions of MIEF2 are still largely unclear in human cancers, especially in ovarian cancer (OC)." (PMID 33317572, 2020). "However, the expression, clinical significance and biological functions of MIEF2 are still largely unclear in human cancers, including ovarian cancer (OC)." (PMID 33317572, 2020). "Mitochondrial elongation factor 2 (MIEF2), located in the mitochondrial outer membrane, serves a regulatory role in mitochondrial fission and is upregulated in ovarian cancer." (PMID 35498135, 2022). "Furthermore, MIEF2 (mitochondrial elongation factor 2) increased SREBP1 and SREBP2 by activating ROS/AKT/mTOR signaling to drive the lipid synthesis in ovarian cancer cells." (PMID 35619540, 2022).
breast carcinoma (2 papers, 2019 to 2022). "However, adaptor proteins for Drp-1 on the outer mitochondrial membrane like MID49/MIEF2 or FIS1, were found to be decreased in the basal-like subtype when compared to the other breast cancer subtypes, and no changes among the different subtypes were observed in MFF, another Drp-1 adaptor protein." (PMID 31231612, 2019).
colorectal cancer (2 papers, 2022 to 2024). A primary or metastatic malignant neoplasm that affects the colon or rectum. "Moreover, CRISPR-based KO screening has identified that depletion of MIEF2 promoted oxaliplatin resistance in colorectal cancer through suppressing the mitochondrial apoptosis cascade in colorectal cancer organoids." (PMID 39075259, 2024).
hepatocellular carcinoma (2 papers, 2022 to 2024). A malignant tumor that arises from hepatocytes. "Inhibition of miR-498 or overexpression of MIEF2 restored the proliferative activity, invasive ability, glycolysis, and mitochondrial division in hepatocellular carcinoma cells." (PMID 38779765, 2024). "Therefore, we further investigate the effects of the lncRNA PRR34-AS1/miR-498/MIEF2 axis on the growth, glucose metabolism, and mitochondrial division in hepatocellular carcinoma cells." (PMID 38779765, 2024). "To determine whether ASOs can be used to modulate mitochondrial dynamics, we administered a panel of ASOs targeting mitochondrial fusion and fission factors (Mfn1, Mfn2, Drp1, Fis1, Mff, Mief1, Mief2) to MHT (mouse hepatocellular carcinoma) cells in culture." (PMID 34698563, 2022).
metastatic melanoma (2 papers, 2021 to 2024). A melanoma that has spread from its primary site to another anatomic site. "The expression of the LLGL1 gene was found to be upregulated by ALKBH5 in xenograft tumours, while ALKBH5 and MIEF2 were upregulated together in the T regulatory cells of metastatic melanoma." (PMID 39596561, 2024). "The findings showed that ZNF775, GBA, ALKBH5, ZFYVE1, and MIEF2 were significantly upregulated in Treg cells of metastatic melanoma compared with primary melanoma." (PMID 34159752, 2021).
Mitochondrial myopathy (2 papers, 2018). "Thus, our data suggest that mutations in MIEF2 result in imbalanced mitochondrial dynamics and a combined respiratory chain enzyme defect in skeletal muscle, leading to mitochondrial myopathy." (PMID 29361167, 2018). "Here we report a patient with mitochondrial myopathy due to a homozygous mutation in MID49 (MIEF2, SMCR7) with combined respiratory chain enzyme defect and augmented mitochondrial fusion in the patient`s skeletal muscle and fibroblasts." (PMID 29361167, 2018).
diabetes (1 paper, 2019). "We observed that LV expression of Mief1 and USP30 were significantly reduced in diabetic mice, although several other genes assessed (Mief2, Park2 and Park6) were not affected by the presence of diabetes." (PMID 31798462, 2019).
liver cancer (1 paper, 2024). An epithelial or non-epithelial malignant neoplasm that arises from the liver. "TCGA analysis and immunohistochemistry reveal high expression of the mitochondrial dynamin MIEF2 in liver cancer tissues." (PMID 38779765, 2024). "MIEF2 was expressed at significantly greater levels in liver cancer tissues than in normal tissues, and the overall survival rate was lower in patients with high MIEF2 expression than in those with low MIEF2 expression." (PMID 38779765, 2024). "The percentage of positive MIEF2 expression among all adjacent tissues was 10%, but that for liver cancer tissue was 80%." (PMID 38779765, 2024). "However, inhibiting miR-498 or increasing the expression level of MIEF2 reversed this downwards trend, mediated mitochondrial division, promoted glucose metabolism reprogramming, and restored the proliferation and growth of liver cancer cells." (PMID 38779765, 2024).
ovarian tumor (1 paper, 2021). "In the cholesterol synthesis pathway, SREBP2 is upregulated by salt-inducible kinase 2 (SIK2), an AMPK-related kinase, and mitochondrial elongation factor 2 (MIEF2)-activated PI3K/AKT or ROS/AKT/mTOR signaling, thus, leading to the promotion of ovarian tumor growth." (PMID 34820325, 2021).
tumor (9 papers, 2020 to 2025). "Similarly, we found that MIEF2 overexpression also promoted ROS production in OC cells, suggesting hyper-activation of mitochondrial fission is a major cause of mitochondrial ROS production in tumor cells." (PMID 33414447, 2021). "Although it is generally accepted that mitochondrial fission is seen as promoting tumor growth and metastasis, the role of fission promoting receptor MiD49 (also known as MIEF2) in metastasis remains controversial." (PMID 35356277, 2022). "MIEF2 was significantly downregulated in tumor tissues compared to normal tissues, and the same trend existed in COAD and READ: lower expression in CRC tumors with advanced TNM stage." (PMID 36106106, 2022). "In the present study, we demonstrate that, as one of the key regulators of mitochondrial fission, MIEF2 significantly enhanced the fatty acid a synthesis and cholesterol biosynthesis in OC cells, which contributed to both tumor growth and metastasis." (PMID 33414447, 2021). "As expected, a significantly down-regulation of miR-424-5p was observed in tumor tissues of OC as compared to their normal counterparts from 30 OC patients, indicating that MIEF2 over-expression is mainly mediated by the down-regulation of miR-424-5p in OC." (PMID 33317572, 2020). "Subcutaneous tumor models further confirmed that knockdown of MIEF2 significantly attenuated the growth abilities of OC cells in nude mice." (PMID 33317572, 2020). "Immunochemistry (IHC) staining showed significantly decreased MIEF2 expression in shMIEF2 tumor tissues compared to shCtrl, implying that the tumor growth inhibiting effect was exerted by MIEF2 knockdown." (PMID 33317572, 2020). "Furthermore, we demonstrated that the down-regulation of miR-424-5p contributed to MIEF2 up-regulation and thus tumor growth and metastasis in OC." (PMID 33317572, 2020). "We then explored the in vivo tumor-promoting effects of MIEF2 in OC." (PMID 33317572, 2020). "MIEF2 was significantly higher in tumor tissues of OC compared to peritumor tissues." (PMID 33317572, 2020). "In addition, a significant negative correlation was observed between the levels of miR-424-5p and MIEF2 in tumor tissues from 30 OC patients." (PMID 33317572, 2020). "Moreover, we found that enhanced aerobic glycolysis was involved in MIEF2-promoted tumor growth and metastasis." (PMID 33317572, 2020). "Considering that increased fatty acid and cholesterol biosynthesis has been coupled with various malignant phenotypes of cancer cells, including tumor growth and metastasis, we therefore tested whether MIEF2 promote OC growth and metastasis through enhancing fatty acid and cholesterol synthesis." (PMID 33414447, 2021). "In addition to tumor growth, the role of MIEF2 in the metastasis of OC cells was also investigated." (PMID 33317572, 2020). "Compared with that in the shRNA-PRR34-AS1 group, the tumor volume was significantly reduced in the sh-PRR34-AS1+miR-498 antagomir and sh-PRR34-AS1+ov-MIEF2 groups (P<0.01)." (PMID 38779765, 2024). "TEM revealed a significant reduction in the number of mitochondria, irregularly shaped nuclei, and uneven chromatin distribution in tumor cells in the sh-PRR34-AS1 group, which were greater in the sh-PRR34-AS1+miR-498 antagomir and sh-PRR34-AS1-ov-MIEF2 groups." (PMID 38779765, 2024).
cancer (6 papers, 2020 to 2024). A tumor composed of atypical neoplastic, often pleomorphic cells that invade other tissues. "MIEF2 may play an important role in cancer development, mitochondrial division and glucose metabolism." (PMID 38779765, 2024). "However, the role of MIEF2 in lipid metabolism reprogramming of cancer cells is still largely unclear." (PMID 33414447, 2021). "However, it is still unclear how MIEF2 is expressed and biologically activated in human cancers." (PMID 38779765, 2024). "Given that increased fatty acid and cholesterol biosynthesis provides not only building blocks but also signaling molecules that are required for cancer growth and metastasis, we therefore tested whether MIEF2-promoted lipid synthesis was involved in the growth and metastasis of OC." (PMID 33414447, 2021). "Our findings showing that MIEF2 up-regulated SREBP1 and SREBP2 expressions in OC cells, further supporting the crucial roles played by both SREBP1-mediated de novo lipogenesis and SREBP2-mediated cholesterol biosynthesis in the progression of cancer." (PMID 33414447, 2021). "Consistently, our data show that MIEF2 promoted the de novo fatty acid synthesis of OC cells through up-regulation of the lipogenic enzymes of ACC1, FASN and SCD1, which further support the oncogenic role for dysregulated lipogenic enzymes in the promotion of cancer progression." (PMID 33414447, 2021). "Consistent with our present findings of MIEF2 in OC, increased expressions of mitochondrial dynamic proteins such as DRP1 (dynamin related protein 1), mitofusin 1 (MFN1) and mitofusin 2 (MFN2) have also been reported in human cancers of liver, lung, colon and breast." (PMID 33317572, 2020).
MIEF2 also shares sentences with these, for which no sentence is quoted: pulmonary arterial hypertension (5 papers); pancreatic cancer (3); acute myocardial infarction (2); optic atrophy (2); atherosclerosis (1); Atrophy (1); cardiovascular disease (1); centronuclear myopathy 1 (1); Encephalopathy (1); melanoma (1); non-small cell lung carcinoma (1); peripheral neuropathy (1); pulmonary hypertension (1); vasculopathy (1).